ADNP (activity dependent neuroprotector homeobox)
Diseases named in the same sentence as ADNP in open-access papers (continued):
Sharing a sentence is not in itself a finding about the gene and the disease.
Intellectual disability (21 papers, 2018 to 2025). "Mutations of the ADNP gene can lead to Helsmoortel-van der Aa syndrome, which includes intellectual disability, developmental delay, ASD and facial dysmorphic features." (PMID 37035742, 2023). "Recently, a number of patients with ASD, intellectual disability and various shared clinical features caused by mutations in Activity-Dependent Neuroprotective Protein (ADNP) have been reported." (PMID 30679581, 2019). "Mutations in ADNP have been recently associated with intellectual disability and autism spectrum disorder." (PMID 30679581, 2019). "Over the last 4 years it became apparent that the mutated ADNP gene is consistently reported as one of the most frequent causes of syndromic autism and intellectual disability." (PMID 30534048, 2018). "Our study conducted a thorough characterization of the clinical manifestations in 15 children with ADNP variants, and revealed a broad spectrum of symptoms including global developmental delay, intellectual disability, ASD, facial abnormalities, and other features." (PMID 38254177, 2024). "The ADNP-gene-related neurodevelopmental disorder Helsmoortel–Van der Aa syndrome is a rare syndromic-intellectual disability—an autism spectrum disorder first described by Helsmoortel and Van der Aa in 2014." (PMID 36553633, 2022). "Furthermore, ADNP variants have been identified as one of the most common single-gene causes of autism spectrum disorder (ASD) and intellectual disability." (PMID 38254177, 2024). "For instance, mutation of the microglia activity-dependent neuroprotective protein (ADNP) has been observed in ASD patients, especially in male patients with more severe intellectual disability." (PMID 31071949, 2019).
autism spectrum disorder (19 papers, 2018 to 2025). A spectrum of developmental disorders that includes autism, and Asperger syndrome. "In conclusion, GSFA allowed us to characterize the transcriptional effects of six autism spectrum disorder risk genes, including ADNP and SETD5, whose effects were largely missed in the original study." (PMID 37770710, 2023). "Because ADNP, which contains 9 zinc fingers and a homeodomain, showed the highest peptide abundance across three replicates, is enriched in RHΔ-Turbo compared to Turbo alone, and is relevant to autism spectrum disorders, we chose to further examine its function at R-loops." (PMID 35013239, 2022).
tauopathy (18 papers, 2014 to 2025). Neurodegenerative disorders involving deposition of abnormal tau protein isoforms (tau proteins) in neurons and glial cells in the brain. "Similar increases, including increases in Tau deposition (tauopathy), were observed in the Tyr mice, mimicking the most abundant ADNP mutation in children." (PMID 36945042, 2023). "An eight-amino-acid peptide, NAP (NAPVSIPQ), identified as the smallest active snippet of ADNP, protects against ADNP deficiencies, including tauopathy and cognitive deficits and displays potent neuroprotection against multiple toxic insults." (PMID 31664177, 2021). "ADNP deficiency has been associated with aging-related increase in tauopathy with Adnp+/- mice exhibiting age-driven tauopathy, neurodegeneration, and cognitive deficits." (PMID 31664177, 2021). "The large fusiform gyrus library (117 subjects) with high sequencing coverage correlated the c.2187_2188insA ADNP mutation frequency to Braak stage (tauopathy) and showed more ADNP mutations in AD specimens." (PMID 31664177, 2021). "This is in line with the findings of tauopathy in the human postmortem ADNP case and with mutated human ADNP reducing Tau–MT interaction, which is corrected/normalized by CP201 treatment." (PMID 33329371, 2020). "Here, having postmortem tissues from 7-year-old male, heterozygous for an ADNP de novo mutation c.2244Adup/p.His559Glnfs*3, we concentrated on a potential tauopathy outcome in this young ADNP subject." (PMID 32661233, 2020). "NAP enhanced Tau—microtubule binding in the face of ADNP mutation, which is potentially protective against juvenile tauopathy." (PMID 32661233, 2020). "The unique availability of multiple postmortem brain sections of a 7-year-old male, heterozygous for ADNP de novo mutation c.2244Adup/p.His559Glnfs*3 allowed exploration of tauopathy, reflecting on a general unexplored mechanism." (PMID 32661233, 2020). "In mice, NAP protects against tauopathy and cognitive deficiencies in a model of ADNP haploinsufficiency and provides protection in transgenic models of FTD and AD." (PMID 26578950, 2015). "NAP (davundetide), a novel drug candidate derived from ADNP, increases ADNP-microtubule association and protects against tauopathy and cognitive deficiencies in mice." (PMID 26578950, 2015). "While complete ADNP deficiency is lethal, ADNP heterozygous mice (ADNP+/−) exhibited cognitive deficits, significant increase in phosphorylated tau, tangle-like structures (tauopathy), reduced neuronal survival and neurodegeneration." (PMID 24489906, 2014). "ADNP deficiencies and ADNP gene mutations in transgenic mice cause dramatic alterations in mRNA/protein expression profiles as well as slower microtubule-dependent axonal transport, aberrant dendritic spine formation, and tauopathy." (PMID 37759476, 2023). "Furthermore, we revealed an accumulation of somatic mutations in the ADNP gene in post-mortem Alzheimer’s disease brains and correlated this accumulation with the progression of tauopathy." (PMID 37759476, 2023). "Using postmortem AD and control brains (olfactory bulbs and hippocampi), we revealed a hotspot for somatic AD ADNP mutations including the novel frameshift, c.2187_2188insA, p.Arg730Thrfs*4 with mutation frequency correlated to Braak stage (tauopathy) and aging." (PMID 31664177, 2021). "Tauopathy was explained by direct ADNP mutation inhibition of Tau–MT binding." (PMID 33329371, 2020). "In mice, ADNP is essential for brain formation and ADNP haploinsufficiency is associated with cognitive and social deficits and tauopathy." (PMID 26578950, 2015). "Essential for brain formation and protective against tauopathy, activity-dependent neuroprotective protein (ADNP) is critical for neurogenesis and cognitive functions, while regulating steroid hormone biogenesis." (PMID 39715923, 2025). "Conversely, cocaine was suggested to induce Tau hyperphosphorylation leading to tauopathy, paralleled by ADNP changes in the face of tauopathy." (PMID 39251453, 2024).
tauopathy (continued). "Other links between ADNP and Tau include increased mRNA and protein levels in the tauopathy mouse model compared to the wild-type littermates until the age of three months." (PMID 36945042, 2023). "The Tyr-mouse findings recapitulate the human tauopathy in a seven-year-old-postmortem ADNP p.His559Glnfs*3 brain." (PMID 36945042, 2023). "ADNP functions as a microtubule regulator, enhancing Tau-microtubule binding and protecting against Tauopathy." (PMID 35399934, 2022). "In the transgenic mice that overexpress the mutated tau 4R species in the cerebral cortex, an increase in cortical ADNP has been reported preceding tauopathy." (PMID 35740400, 2022). "Conversely, ADNP deficiencies and ADNP gene mutations in transgenic mice led to dramatic alterations in mRNA/protein expression profiles as well as slower microtubule-dependent axonal transport, aberrant dendritic spine formation and tauopathy, which could be partially repaired by NAP treatment." (PMID 36230962, 2022). "In conclusion, we revealed somatic aging/AD-linked mutations converging on tauopathy, including NAP/ADNP." (PMID 31664177, 2021). "Heterozygous ADNP knockout mice develop tauopathies, possibly due to the fact that NAP interacts with the neuronal microtubule network." (PMID 31029150, 2019). "We have previously discovered that activity-dependent neuroprotective protein (ADNP) is essential for brain formation in the mouse, with ADNP+/− mice exhibiting tauopathy, age-driven neurodegeneration and behavioral deficits." (PMID 24489906, 2014). "ADNP expression was also assessed in a transgenic mouse model for tauopathy, where western blot assessment at different stages in life (3–10.5 months of age) resulted in a specific age-dependent decline of ADNP in the cerebral cortex of Tau-Tg and control mice." (PMID 38926592, 2024). "Furthermore, NAP/ADNP by binding to EB3, which in turn binds Tau, enhance Tau association with the MT shaft, protecting the MTs, MT-regulated axonal transport and inhibiting tauopathy." (PMID 31664177, 2021). "Together these results corroborate ADNP/NAP microtubule-Tau protective mechanism, while offering potential clinical relief against tauopathy." (PMID 32661233, 2020).
Helsmoortel-Van der Aa syndrome (17 papers, 2018 to 2025). "Heterozygous de novo mutations in the Activity-Dependent Neuroprotective Homeobox (ADNP) gene underlie Helsmoortel-Van der Aa syndrome (HVDAS)." (PMID 38926592, 2024). "Re-analysis revealed a heterozygous (de novo) pathogenic ADNP variant that causes Helsmoortel-van der Aa syndrome (OMIM #615873)." (PMID 37460657, 2023). "This work provides important insights into the role of ADNP in neural development which would be useful for understanding the pathology of the Helsmoortel-Van der Aa syndrome caused by ADNP mutation." (PMID 32533114, 2020). "Our work provides important insights into the role of ADNP in neural development and the pathology of the Helsmoortel-Van der Aa syndrome caused by ADNP gene mutation." (PMID 32533114, 2020). "ADNP mutations in Helsmoortel-Van der Aa syndrome are of heterozygous nature, and therefore presence of both wild-type and truncated ADNP could promote competition, thereby impacting protein detection levels." (PMID 38926592, 2024). "De novo mutations in ADNP have been recently linked to the Helsmoortel-Van der Aa syndrome." (PMID 32533114, 2020). "Together, this study shapes awareness for critical western blot assessment of ADNP specific protein variants with the eye on future functional studies by combined antibody-based detection methods in order to unravel the mutational mechanism underlying the Helsmoortel-Van der Aa syndrome." (PMID 38926592, 2024). "ADNP (Activity Dependent Neuroprotective Protein) is proposed as a neuroprotective protein whose aberrant expression has been frequently linked to rare neural developmental disorders and cancers, including the recently described neurodevelopmental Helsmoortel-Van der Aa syndrome." (PMID 32714933, 2020). "More clinical reports of patients with mutations in ADNP are needed to determine whether Helsmoortel-van der Aa syndrome should be regarded as part of the SSRIDD spectrum due to the clinical overlap and the functional interaction between ADNP and the SWI/SNF complex." (PMID 30123105, 2018). "Taken together, our protein enrichment strategy using immunoprecipitation was successful in capturing wild-type ADNP and various truncating variants in HEK293T overexpression systems but failed to enrich a native mutant protein in patients with Helsmoortel-Van der Aa syndrome." (PMID 38926592, 2024).
Cognitive impairment (13 papers, 2016 to 2024). Abnormal cognition is characterized by deficits in thinking, reasoning, or remembering. "Davunetide, a derivative octapeptide of ADNP, has been shown to ameliorate some of the cognitive deficits in animal models with ADNP mutations, which is a promising line of therapeutic research for ADNP patients with similar defects." (PMID 26917491, 2016). "Importantly, ADNP is a master regulator of >400 genes, essential for brain formation, while its haploinsufficiency causes cognitive impairments." (PMID 31992971, 2019). "In contrast, ADNP haploinsufficiency provoked important cognitive impairment and delayed motor development." (PMID 38673966, 2024). "ADNP-haploinsufficient mice exhibit age-related tauopathy, neurodegeneration, and cognitive deficits." (PMID 35740400, 2022). "Our discovery of the requirement of ADNP for brain formation coupled with the finding that a major phenotypic outcome of ADNP haploinsufficency in mice leads to cognitive impairments, placed ADNP as a key regulatory gene for brain function." (PMID 30534048, 2018). "While complete knockout of ADNP is lethal, haploinsufficient (heterozygous) mice survive, showing cognitive impairment." (PMID 30534048, 2018). "Autistic individuals with LoF variants in the four moderate-risk genes (NAV3, ITSN1, SCAF1 and HNRNPUL2; n = 95) have less cognitive impairment than 129 autistic individuals with LoF variants in highly penetrant genes (CHD8, SCN2A, ADNP, FOXP1 and SHANK3) (59% vs 88%, P = 1.9 × 10−6)." (PMID 35982159, 2022).
developmental delay (10 papers, 2018 to 2024). "Developmental disorders caused by mutations in GATAD2B (OMIM 615074), ADNP (OMIM 615873), BCOR (OMIM 300166) and NR2F1 (OMIM 615722) have features that overlap with those of TBR1-related disorder, including developmental delay, ID, speech and language impairments and autistic behaviors." (PMID 36579832, 2023). "With this uncertainty, clinical labs frequently report rare missense variants in ADNP as uncertain significance (VUS), affecting a significant portion of patients with non-specific developmental delay (DD), ID, and/or ASD." (PMID 31029150, 2019).
neuroblastoma (8 papers, 2020 to 2024). Neuroblastoma (NB) is the most common solid, extracranial childhood tumor. "In addition, ADNP was also shown to bind LC3 directly in a human neuroblastoma cell line, and its association was increased in the presence of the NAP (Davunetide) octapeptide." (PMID 38637827, 2024). "In 2021, co-immunoprecipitation experiments on human neuroblastoma protein extracts revealed an indirect interaction of the NAD+-deacetylase enzyme SIRT1 with ADNP through the microtubule-end binding proteins EB1/EB310." (PMID 38926592, 2024). "The results revealed ADNP was negatively associated with the stromal score in GBM (r = -0.46), WT (r = -0.43), and neuroblastoma (NBL) (r = -0.52)." (PMID 37525242, 2023). "As such, neuronal-like N1E-115 mouse neuroblastoma cells were co-transfected with plasmids expressing EB3-red fluorescence protein (RFP) and green fluorescence protein (GFP)–ADNP or GFP-mutated-ADNP and subjected to live cell imaging." (PMID 37759476, 2023). "Genome editing (CRISPR/Cas9) in N1E-115 neuroblastoma cells to form neuron-like cell lines expressing ADNP-mutant proteins conjugated to GFP indicated distinct cellular phenotypes depending on the mutation location." (PMID 36945042, 2023). "Moreover, immunoprecipitation experiments with EB1/EB3 antibodies in human neuroblastoma cells revealed co-elution of ADNP and SIRT1." (PMID 36945042, 2023).
bladder cancer (7 papers, 2020 to 2024). "ADNP was a prognostic risk factor for bladder cancer progression after intravesical chemotherapy treatment." (PMID 37627900, 2023). "High ADNP protein expression was significantly associated with poor prognosis of bladder cancer and an increased risk of mortality." (PMID 37627900, 2023). "Moreover, ADNP was found to be associated with cisplatin resistance in bladder cancer in vivo." (PMID 37627900, 2023). "These proteins include LTN1 (ovarian cancer), GBE1, CACNA1E and ADCY10 (lung cancers), as well as PLEKHS1 and ADNP (bladder cancer)." (PMID 38951817, 2024). "The knockdown of ADNP in bladder cancer cell lines significantly reduced cell proliferation and migration, which in turn, increased cisplatin resistance." (PMID 37627900, 2023). "Transcriptional assessment of ADNP levels in a large cohort of bladder cancer specimens highlighted a significant overexpression in the patients with tumor progression and the association of higher ADNP protein levels to poor prognosis in such patients." (PMID 36945042, 2023). "ADNP is highly expressed in bladder cancer, wherein the mRNA and protein expression of ADNP was significantly upregulated in bladder cancer tissues as compared to normal bladder tissues." (PMID 37627900, 2023). "The knockdown of ADNP markedly reduced bladder cancer cell proliferation in vitro, the growth of bladder cancer in vivo, and G1/S phase transition of the cell cycle." (PMID 37627900, 2023). "Activity-dependent neuroprotective protein (ADNP) has been regarded as an oncogene in bladder cancer and ovarian cancer." (PMID 37525242, 2023). "In another study, ADNP was found to promote bladder cancer cell migration via TGF-β-mediated epithelial-mesenchymal transition (EMT) pathway." (PMID 36945042, 2023). "In conclusion, the mRNA and protein expressions of ADNP were up-regulated in human bladder cancer and reveal its role as a tumor promoter with effects on tumor cell proliferation as well as cell cycle with the activation of AKT pathway." (PMID 33240802, 2020). "In addition, the overexpression of ADNP also facilitated the development of human bladder cancer via triggering the cell cycle transition process from the GI phase to the S phase through the AKT pathway." (PMID 37525242, 2023). "Taken together, ADNP is overexpressed in bladder cancer and may act as an oncogene in bladder tumorigenesis." (PMID 37627900, 2023). "Besides, the upregulated expression of ADNP enhances tumorigenesis in some human tumors like bladder cancer (BC)." (PMID 34335928, 2021). "ADNP expression in bladder cancer and its correlation with clinicopathological characteristics." (PMID 33240802, 2020). "ADNP is important for cell signalling and cancer growth and has been suggested as a potential as a biomarker and / or therapeutic target for gastric and colorectal cancer, hepatocellular carcinoma, glioblastoma multiforme, Bladder cancer, ovarian cancer, and breast cancer." (PMID 39480826, 2024). "Hence, ADNP may be a novel molecular target for predicting prognosis in bladder cancer as well as adjuvant therapeutic for bladder cancer patients receiving intravesical chemotherapy." (PMID 37627900, 2023). "Both the mRNA and protein expression of ADNP were significantly higher in patients with progressive bladder cancer as compared to those with non-progressive bladder cancer." (PMID 37627900, 2023).
bladder cancer (continued). "Moreover, the results also represented ADNP expression was positively correlated with a poorer prognosis, higher histologic grade, and progressive pathologic stage in HCC, which was following the previous studies in bladder cancer and HGSOC." (PMID 37525242, 2023). "Previous studies have reported that ADNP can activate the AKT pathway to promote the neuronal growth and differentiation, which is related to the up-regulation of the expression of AKT phosphorylated kinase, and this mechanism may also exist in bladder cancer." (PMID 33240802, 2020).